PON1 (paraoxonase 1)
Diseases named in the same sentence as PON1 in open-access papers (continued):
Sharing a sentence is not in itself a finding about the gene and the disease.
Obesity (continued). "While our study and previous proteomics analysis measured the total PON1 protein abundance, another study showed that PON1 enzymatic activity is reduced in COVID-19, cancer, and obesity compared to healthy controls." (PMID 38672194, 2024). "For instance, a study involving 20 individuals with severe obesity (BMI > 50 kg/m2) reported an increase in antioxidant potential, accompanied by elevated paraoxonase 1 protein levels 6 months after BS." (PMID 39574780, 2024). "This study thereby reinforces the genetic foundation of PON1 in obesity and various MASLD-related liver features, by extending previous findings from common variants to include rare variants." (PMID 39334710, 2024). "Obesity has also been found to be involved in lower PON1 activity and higher levels of HDL and LDL hydroperoxides, meaning more oxidative stress." (PMID 38474211, 2024). "When comparing individuals with obesity to lean controls, significant results were obtained for the PON1 gene." (PMID 39334710, 2024). "The proportion of the PON1 rs854560 adenine pairs (AA) genotype was significantly higher in patients with obesity with MASLD than in healthy controls (93.0% vs. 87.0%, p = 0.043)." (PMID 38836837, 2024). "Obesity leads to a higher chance of developing cardiovascular disease and moreover, the body index is directly related to PON1." (PMID 38474211, 2024). "PON1 activity is known to be reduced in patients suffering from hypercholesterolemia and obesity, and it was established as a predictive factor of cardiovascular diseases." (PMID 36833509, 2023). "an inverse correlation between PON1 AREase activity and BMI is thought to result from elevated oxidative stress, which accompanies metabolic disorders such as obesity." (PMID 36833509, 2023). "As independent PON-1 predictors, TBARS, leptin, and adiponectin levels demonstrate the significance of obesity in the control of PON-1." (PMID 37107203, 2023). "Regardless, in this study we observe a clear and consistent increase of PON1 levels and activity along with significant amelioration of obesity and hyperlipidemia with vutiglabridin treatment." (PMID 37189434, 2023). "To gain insight into the changes in serum antioxidant and anti-inflammatory activities associated with obesity/GDM, we examined the activity of the HDL-associated enzyme PON1 and the total antioxidative capacity of serum." (PMID 36671061, 2023). "Our results suggest, for the first time, that the effects of vutiglabridin against obesity and hyperlipidemia are, in part, mediated by the modulation of PON1 levels and activity." (PMID 37189434, 2023). "Exploring the relationship between PON1-related variables and the presence of liver alterations in patients with obesity is an area of great scientific interest." (PMID 38136158, 2023). "Decreased PON1 was reported among patients with a diet that was rich in high fat, and obese patients, since obesity has multidirectional interrelations with psoriasis." (PMID 35888704, 2022). "Recent advances from association, (epi)genetic and animal studies further emphasize a protective role of PON1 against environmental exposure, obesity and NAFLD." (PMID 34389043, 2021). "Current PON1 research in obesity and NAFLD focused on either genetic, epigenetic or functional data to explain its function in pathophysiology." (PMID 34389043, 2021). "Although our study consists of an extensively monitored large obesity cohort with(out) the presence of hepatic manifestations, we only had restricted information on other variables known to influence PON1 status." (PMID 34389043, 2021). "The observed increase in PON1 activity levels would in this manner reflect a defence mechanism to prevent further hepatometabolic manifestations that lead to the advancement of obesity to NAFLD/NASH." (PMID 34389043, 2021). "We demonstrate significantly reduced PON-1 activity in people with obesity and small nerve fibre damage." (PMID 34131170, 2021).
Obesity (continued). "In humans, studies have observed that individuals with obesity have impaired PON1 activity and impaired mitochondrial function." (PMID 34356595, 2021). "The other four haplotypes were associated with obesity when it was classified by BFP; one of them in GPX3, two others in PON1, and the last one in PON2 and PON3." (PMID 32752212, 2020). "Another group of relevant antioxidant enzymes associated with obesity is the paraoxonase family (PON1, PON2, PON3), among which PON1 is the most studied one." (PMID 32752212, 2020). "We found two haplotypes associated with obesity by BMI (in GPX3 and in GPX5 and GPX6) and five haplotypes associated with obesity by PBF (in GPX3, in PON1, and in PON2 and PON3)." (PMID 32752212, 2020). "In the case of PON1 activity in the context of obesity, some studies have found decreased paraoxonase and arylesterase activities in the obese, whereas others have not." (PMID 24562334, 2014). "A few studies in adults and adolescents suggest a link between obesity and paraoxonase 1 (PON1), a multifunctional enzyme that can metabolize organophosphate pesticides and also has antioxidant properties." (PMID 23658746, 2013). "Although we identified some meaningful relationships of obesity with both PON1 and genetic ancestry, this study does have some limitations." (PMID 23658746, 2013). "In this study, we examined the relationship between PON1 genotype and status with obesity in young Mexican-American children from the Salinas Valley, CA." (PMID 23658746, 2013). "Other studies looking at the relationship of PON1 genotype with obesity among adults have been inconsistent." (PMID 23658746, 2013). "Despite these limitations, our findings suggest an intriguing role of PON1 in obesity and underscore the importance of accounting for differences in genetic ancestry in studies of PON1 and health outcomes." (PMID 23658746, 2013). "In this paper, we extend our studies of the CHAMACOS birth cohort to examine the association of PON1 status (modeled as PON1192 genotype and arylesterase activity) with outcomes of growth and obesity in young children at ages two and five years." (PMID 23658746, 2013). "We determined PON1192 genotype and arylesterase levels (ARYase, measure of PON1 enzyme quantity), to characterize the relationship between PON1 and obesity in young Mexican-American children (n = 373) living in an agricultural community in California." (PMID 23658746, 2013). "We already reported that polymorphisms of the PON1 and NPY genes, which were associated with stroke and obesity, were related to DP among Korean stroke patients." (PMID 23043591, 2012). "The impact of obesity on the activity of PON1 follows an inverse relationship." (PMID 40353441, 2025). "The paraoxonase (PON) gene family (including PON1, PON2, and PON3), is known for its anti-oxidative and anti-inflammatory properties, protecting against metabolic diseases such as obesity and metabolic dysfunction-associated steatotic liver disease (MASLD)." (PMID 39334710, 2024). "Reduced serum PON1 activity is found in diseases marked by oxidative stress and inflammation, but its role in obesity remains unclear." (PMID 38136158, 2023). "Overall, our results demonstrate that PON1 is a direct, interacting target of vutiglabridin, and that the modulation of PON1 by vutiglabridin may provide benefits for the treatment of hyperlipidemia and obesity." (PMID 37189434, 2023). "Another complicating factor is the fact that PON1 is primarily synthesized in the liver, and individuals with obesity often exhibit non-alcoholic fatty liver disease (NAFLD), which could affect the measurement results." (PMID 38136158, 2023). "Overall, our results demonstrate that rePON1 is a direct interacting target of vutiglabridin, and that the modulation of PON1 by vutiglabridin may be used a potential therapeutic against obesity and hyperlipidemia." (PMID 37189434, 2023).
Obesity (continued). "Empagliflozin may protect the heart by altering the expression of genes including Apoe, Apoc1, Saa2, Apoa2, and Pon1, which are all involved in lipid metabolism disturbance in obesity." (PMID 36242090, 2022). "In a study with 117 Mexican children 6–12 years old, the PON1 rs662 polymorphism was associated with insulin resistance but not with overweight or obesity, in agreement with our study." (PMID 32752212, 2020). "Moreover, PON1 levels and activity are significantly impaired in individuals with cardiovascular and liver diseases, as well as in DM and obesity." (PMID 31430977, 2019). "Here we showed that sex not only might affect arylesterase and lactonase activities of PON1, but also it affects their relationship with clinical measures of obesity, such as BMI and waist circumference." (PMID 31138960, 2019). "Again, PON1, with its antiatherogenic properties, might be an ideal candidate in the pathophysiology of obesity." (PMID 31430977, 2019). "We also determine the relationship between genetic ancestry and childhood obesity in these children and additionally whether it confounds the effect of PON1 on obesity." (PMID 23658746, 2013). "Data on the relationship between PON1 and obesity, especially in children, are limited." (PMID 23658746, 2013). "Despite pronounced differences in PON1 allele frequencies and obesity prevalence between ethnic groups, no studies of PON1 genetics and obesity have adjusted for potential genetic confounding." (PMID 23658746, 2013). "Data on the relationship between obesity and PON1 genotypes has been limited and inconsistent." (PMID 23658746, 2013). "Additionally, obesity in PCOS may influence PON1 levels and activity indirectly, through its impact on oxidative stress." (PMID 41607469, 2026). "Lower baseline PON1 activity measured by both arylesterase and lactonase functions and higher levels of the oxylipins PGE2, LTB4, and 15-HETE were significant predictors of SAD on longitudinal CT after controlling for other known RA-LD risk factors such as smoking, obesity, and RA disease duration." (PMID 36138190, 2023). "Moreover, some results, such as the intriguing inverse relationship between the serum PON1 concentration and the degree of steatosis or the loss of influence of the R allele in ARE activity in patients with obesity, raise new questions and merit further scientific investigation." (PMID 38136158, 2023). "Further examination of DEPs revealed that following empagliflozin treatment, the expressions of Apoe, Apoc1, Saa2, Apoa2, and Pon1 altered dramatically, suggesting that these proteins may be the main proteins that empagliflozin uses to treat obesity-induced aberrant lipid metabolism." (PMID 36242090, 2022). "Interestingly, contrary to other studies reporting a relationship between inflammatory markers and PON1 in certain subgroups, obesity, sex and age do not seem to modify the associations in this population-based sample." (PMID 34332593, 2021). "In addition, obesity alters the composition of HDL in a manner that may impair binding of PON1 to HDL surface such as lowering both HDL's largest subfraction (HDL2) and its major binding protein (apo A1)." (PMID 24799979, 2014). "Furthermore since studies suggest genetic admixture may influence obesity parameters, it is of critical importance to adjust for genetic ancestry as a potential confounder in studies of PON1 and obesity in admixed populations." (PMID 23658746, 2013). "Overall, these data suggest that PON1 genotype and protein expression may play a role in obesity." (PMID 23658746, 2013). "Interestingly, neither obesity nor GDM was associated with altered PON1 activity." (PMID 36671061, 2023). "Patients with obesity had elevated serum triglycerides and SAA and lower HDL-C, PON-1 activity and cholesterol efflux." (PMID 34131170, 2021). "In this research, three haplotypes; two in PON1, and one PON2 and PON3, were found to be risks factor for obesity." (PMID 32752212, 2020).
Obesity (continued). "Since adipokines represent a molecular link between obesity and CVD, we here explored the possible impact of these substances on PON1 activity/expression." (PMID 31390816, 2019). "Several of the observed DMCs were located in genes related to T2D or obesity, such as ALOX12, PAMR1, and GNAS in WB; IRS1, LEP, and ADIPOQ in SAT; LCAT, FOXA2, KCNQ1, and GCKR in VAT; and PKD4, HNF4A, XBP1, and PON1 in LT." (PMID 29466957, 2018). "QTL for NVD was homologous with HSA 17q21 regions which contained many obesity candidate genes including PPY, PON1 and 2, GAST, PNMT, STAT3 and HCRT." (PMID 23977060, 2013). "The PON1 status models for five year olds indicated a statistically significant interaction between ARYase and PON1192 genotype for waist circumference and obesity status (p = 0.15 and 0.13, respectively)." (PMID 23658746, 2013). "The level of PON-1 decreases in diabetics, in those with KVH, in those who smoke, in hypercholesterolemia, in old age, in obesity, in menopause and in renal insufficiency." (PMID 23780417, 2013). "Obesity has been shown to affect PON1 activity, but we neither detected obesity nor GDM-related changes in PON1 activity in pregnant mothers or their offspring." (PMID 36671061, 2023). "Nonetheless, to the current researchers’ knowledge, no studies have yet been conducted to investigate the effects of physical activity, without dietary intervention, on MPO levels and on the MPO/PON1 ratio in obesity." (PMID 37887393, 2023). "The results demonstrated that supplementation of strawberries with a regular diet reduced PON1 activity and did not improve lipids profiles in healthy subjects without obesity." (PMID 35883764, 2022). "Circulating apolipoprotein A1 (P = 0.009), HDL cholesterol (HDL-C) (P < 0.0001), cholesterol efflux (P = 0.002) and paroxonase-1 (PON-1) activity (P < 0.0001) were lower, and serum amyloid A (SAA) (P < 0.0001) was higher in participants with obesity compared to controls." (PMID 34131170, 2021). "In addition, obesity significantly interacted with FGA rs2070016, PON1 rs854555 and EDNRA rs5333 on fibrinogen (P = 0.024, 0.036, and <0.001, respectively)." (PMID 32214403, 2020). "In fact, the interest on this protein has increased due to evidences that decreased PON1 activity is related to several non-communicable diseases, such as cancer, obesity, DM, CVD, neurodegenerative diseases, and NAFLD." (PMID 31430977, 2019). "Similar findings have been observed in children, with some authors observing altered PON1 activities, and others finding no PON1 activity changes in obesity in children." (PMID 24562334, 2014). "Furthermore, the PON-1 level was higher in cases with obesity compared to non-obese cases; however, the difference was not significant (p = 0.330)." (PMID 39336967, 2024). "The activity of SOD and PON1 was not dependent on gender, degree (BMI) or type of obesity (WHR)." (PMID 37511388, 2023). "Obesity plays an essential role in the occurrence of PCOS and may affect the PON-1 levels." (PMID 34754696, 2021). "The aim of this study was to evaluate the levels of paraoxonase 1 (PON1), lectin-like oxidized LDL receptor-1 (LOX-1), antioxidant enzymes (superoxide dismutase (SOD), catalase (CAT), and glutathione peroxidase (GPx)), and lipid peroxidation processes in the course of obesity." (PMID 31737129, 2019). "Our findings suggest that PON1 may play a role in obesity independent of genetic ancestry and that studies of PON1 and health outcomes, especially in admixed populations, should account for differences due to population stratification." (PMID 23658746, 2013).
Obesity (continued). "Although PON1 status, which accounts for both PON1 quantity and enzyme activity, is considered more informative than looking at genotype alone, no other studies have examined the effect of PON1 status on obesity." (PMID 23658746, 2013). "Therefore, alterations in the levels of PON1-related variables may not be the same as those occurring in milder obesity." (PMID 38136158, 2023). "PON1 arylesterase activity correlated negatively with chemerin concentration when analysing the whole study population or the NDO individuals, which indicates the impact of obesity on antioxidant capacity even in the absence of manifest insulin resistance or cardiovascular complications." (PMID 24702860, 2014).